RAB5C (RAB5C, member RAS oncogene family)
Description:
The small GTPases Rab are key regulators of intracellular membrane trafficking, from the formation of transport vesicles to their fusion with membranes. Rabs cycle between an inactive GDP-bound form and an active GTP-bound form that is able to recruit to membranes different sets of downstream effectors directly responsible for vesicle formation, movement, tethering and fusion. Involved in early endocytic trafficking. Required for EEA1 recruitment to early endosomes. Required for EGF and transferrin endocytosis and trafficking through early endosomes.
Synonyms: RABL; RAB5CL; L1880; RAB5L
Tractability: Small molecule: a structure with a bound ligand is known. Antibody: its Gene Ontology location is reachable by antibodies, with high confidence; UniProt places it where antibodies can reach, with medium confidence. PROTAC: ubiquitination databases record sites on it; its protein half-life has been measured.
Target class: Enzyme; Hydrolase
Gene: Protein-coding gene on chromosome 17 (42,124,976 to 42,155,044, reverse strand). Ensembl gene ENSG00000108774.
Subcellular location: Cell membrane; Early endosome membrane; Melanosome
Subcellular location (Human Protein Atlas): Endosomes
Pathways (Reactome):
Vesicle-mediated transport: Clathrin-mediated endocytosis; Golgi Associated Vesicle Biogenesis; RAB GEFs exchange GTP for GDP on RABs; TBC/RABGAPs
Disease: Respiratory syncytial virus (RSV) attachment and entry
Immune System: Neutrophil degranulation
Metabolism of proteins: RAB geranylgeranylation
Gene Ontology:
Molecular function: G protein activity; GDP binding; GTPase activity; protein binding; GTP binding
Biological process: endocytosis; endosomal transport; plasma membrane to endosome transport
Cellular component: endosome; extracellular exosome; lipid droplet; lysosomal membrane; melanosome; azurophil granule membrane; early endosome; early endosome membrane; endocytic vesicle; plasma membrane; synaptic vesicle membrane
Genetic constraint (gnomAD): Loss-of-function variants: 3 observed, 18.92 expected, observed/expected ratio (o/e) 0.16, 90% interval 0.071 to 0.41. The upper end of that interval is the gene's LOEUF score, 0.41, which puts it in group 1 of 6, group 1 being the genes least tolerant of losing a copy. Missense variants: 199 observed, 269.82 expected, observed/expected ratio (o/e) 0.74, 90% interval 0.66 to 0.83. Synonymous variants: 100 observed, 103.16 expected, observed/expected ratio (o/e) 0.97, 90% interval 0.82 to 1.14.
Homologues: Orthologues: chimpanzee RAB5C (100% identical), rabbit RAB5C (99% identical), rat Rab5c (99% identical), dog RAB5C (99% identical), mouse Rab5c (99% identical), guinea pig RAB5C (95% identical), tropical clawed frog rab5c (94% identical), zebrafish rab5c (90% identical), rat AABR07009572.1 (81% identical), Caenorhabditis elegans rab-5 (74% identical), Drosophila melanogaster Rab5 (73% identical), pig RAB5C (72% identical). Paralogues in human: RAB5A (88% identical), RAB5B (84% identical), RAB17 (43% identical), RAB11B (41% identical), RAB31 (41% identical), RAB11A (40% identical), RAB21 (40% identical), RAB22A (40% identical), RAB1A (39% identical), RAB1B (38% identical), RAB25 (38% identical), RAB6B (38% identical), and 56 more.
Diseases named in the same sentence as RAB5C in open-access papers:
RAB5C is named in the same sentence as 19 diseases in open-access papers, as found by Europe PMC text mining. Sharing a sentence is not in itself a finding about the gene and the disease. The quoted sentences say what the papers report.
acute lymphoblastic leukemia (2 papers, 2015 to 2020). Leukemia with an acute onset, characterized by the presence of lymphoblasts in the bone marrow and the peripheral blood. "For instance, miR-509 can bind to the transcripts encoding Rab5C, one of the three Rab5 isoforms, thereby inhibiting Rab5C expression in pre-B acute lymphoblastic leukemia cells and resulting in a growth defect that can be rescued by Rab5C overexpression." (PMID 26579118, 2015).
breast carcinoma (2 papers, 2017 to 2021). "RAB5B has been shown to be activated in malignant melanoma, while RAB5C enhances epidermal growth factor-induced progression of breast cancer." (PMID 28103577, 2017). "Furthermore, Rab5c is involved in recycling of integrin beta-1, a potential interactor of EpCAM, which is important for invasiveness of breast cancer cells." (PMID 34693227, 2021).
malignant melanoma (2 papers, 2017 to 2020). "Hypomethylation of TBC1D16 leads to the activation of TBC1D16 transcription in melanoma, and the short isoform of TBC1D16 (TBC1D16-47KDa) promotes melanoma growth and metastasis through interacting with RAB5C and regulating EGFR signaling." (PMID 33194704, 2020).
ovarian carcinoma (2 papers, 2020 to 2023). A malignant neoplasm originating from the surface ovarian epithelium. "Aberrant expression of ANXA5, CD81, and RAB5C affects the sensitivity of ovarian cancer cells to platinum- and paclitaxel-based chemotherapeutic agents." (PMID 37754253, 2023). "Therefore, ANXA5, CD81, and RAB5C may serve as therapeutic targets in drug-resistant ovarian cancer." (PMID 37754253, 2023). "Therefore, downregulating the expression of RAB5C may aid in the treatment of ovarian cancer." (PMID 37754253, 2023).
Papillary Thyroid Cancer (2 papers, 2020 to 2024). "Stratification of papillary thyroid cancer (THCA) TCGA expression data using quartile values (Q3Q4 vs Q1Q2) further highlighted the potential clinical relevance for 5 of these NIS interactors (AP2A2, ARF6, CTTN, HLA-A and RAB5C) on disease recurrence following RAI treatment (P < 0.05)." (PMID 37921808, 2024).
viral infections (2 papers, 2020 to 2022). "In this study, based on the established virus-cell infection model, Singapore grouper iridovirus (SGIV)-infected grouper spleen (GS) cells, we investigated the role of Rab5c in virus infection and host immune responses." (PMID 33013900, 2020). "Many studies have focused on Rab5a, however, few have investigated Rab5c, especially on the impact of virus infection and cellular immune responses." (PMID 33013900, 2020). "However, the role of Rab5c in virus infection and cellular immune responses remains poorly understood." (PMID 33013900, 2020).
diabetes (1 paper, 2020). "Boutchueng–Djidjou’s recent study showed that RAB5C is an endosomal sorting marker that is associated with diabetes." (PMID 32602534, 2020).
Fabry disease (1 paper, 2019). Fabry disease (FD) is a progressive, inherited, multisystemic lysosomal storage disease characterized by specific neurological, cutaneous, renal, cardiovascular, cochleo-vestibular and cerebrovascular manifestations. "The small GTPases Rab5 and EEA1 play a rate-limiting role in membrane docking or fusion in the early endocytic pathway, and our previous study suggested that KCa3.1 is transported into early endosomes via a Rab5c- and EEA1-dependent process in Fabry disease." (PMID 31871552, 2019). "Previously, we demonstrated that PM KCa3.1 proteins are internalized via a clathrin-dependent process and transported in a Rab5c- and EEA1-dependent process in Fabry disease." (PMID 31871552, 2019). "Clathrin-dependent internalization, Rab5c, early endosome antigen-1- (EEA1-) dependent transportation, and lysosomal degradation were involved in globotriaosylceramide-induced KCa3.1 downregulation in Fabry disease." (PMID 31871552, 2019).
mastitis (1 paper, 2021). Inflammation of breast tissue during lactation or postpartum due to an obstructed duct or infection. "RAB5C and MAPK6 genes were identified as candidate genes for mastitis in dairy cattle following intramammary infection with E. coli or S. uberis using a combination of GWAS and DEG data analyses." (PMID 34691146, 2021).
osteoporosis (1 paper, 2025). A condition of reduced bone mass, with decreased cortical thickness and a decrease in the number and size of the trabeculae of cancellous bone (but normal chemical composition), resulting in increased fracture incidence. "In this study, we identified five key genes related to the circadian rhythm in osteoporosis (RAB5C, ECE1, FLT3, FCGR2A, and APPL1) using bioinformatics and machine learning approaches." (PMID 40642528, 2025).
rectal cancer (1 paper, 2020). A primary or metastatic malignant neoplasm that affects the rectum. "More recently, internalization of epidermal growth factor receptor (EGFR) by Rab5C was suggested to enhance resistance to ionizing radiation in rectal cancer." (PMID 32365785, 2020).
thyroid cancer (1 paper, 2022). "In literature, several papers reported that miR-145 is downregulated in thyroid cancer where it acts as a tumor suppressor by impairing cancer cell growth, cell motility, and metastasis through targeting AKT3 and RAB5C genes or by regulating the NF-κB pathway." (PMID 35222800, 2022).
tumor (13 papers, 2013 to 2025). "For instance, miR-145 has been suggested by several studies to act as a tumor suppressor in TC by inhibiting various pathways, including RAB5C, PI3K/AKT3, and protein kinase B." (PMID 39928612, 2025). "In a parallel EGFR pathway, radioresistance of tumor cells that overexpress Rab5C, Ku70, and Ku80 was traced to Rab5C regulation of EGFR internalization and its translocation to the nucleus, where EGFR stimulates Ku70/Ku80 expression." (PMID 34337349, 2021). "Finally, tumor promotion effect of Piezo1 was found to exerted through recruiting and combining Rab5c to activating TGF-β signaling pathway." (PMID 35461277, 2022). "In conclusion, miR-145 functions as a tumor suppressor in PTC by inhibiting RAB5C." (PMID 32788878, 2020). "Furthermore, miR-145 functions as a tumor suppressor in PTC by inhibiting RAB5C." (PMID 36077665, 2022). "IHC analysis of paired tumour tissue samples from 10 patients confirmed the expression of four markers (BTD, ECM1, MBL2, and RAB5C) in both blood and tissues, as demonstrated in our study." (PMID 40545963, 2025). "Although we observed upregulation of all three Rab5 isoforms (Rab5A, Rab5B, Rab5C) in HCC, their individual contributions to lipid metabolism and tumor progression remain undefined." (PMID 40894643, 2025). "Similarly, the downregulation of RAB5C, RAB7A, and DNM2, involved in endocytosis and vesicular trafficking, suggests interference with receptor signaling, nutrient uptake, and protein degradation, essential for tumor growth." (PMID 40429900, 2025). "Finally, proteins involved in tumor migration, invasion, malignancy and cell adhesion (Ctsd or Cathepsin D, MTCO2, Tpd52l2, Rab5c, Smarcc1) were also found to be exclusively expressed or significantly up-regulated by the AI tumorspheres compared to the AD cells." (PMID 29298329, 2018).
infection (10 papers, 2014 to 2026). The state of being infected such as from the introduction of a foreign agent such as serum, vaccine, antigenic substance or organism. "Although we also identified several cellular proteins that interacted with VP088 during infection, such as Rab7 and Rab5C, their detailed roles in SGIV replication needed further investigation." (PMID 41378894, 2026). "The authors proposed that Rab5c is required for efficient virus production at the late step of the infection coordinating trafficking and/or assembly of viral components to the budding sites on cell membranes." (PMID 38675975, 2024). "It has been reported that RAB5C plays critical roles during the infection of flaviviruses including Zika virus and Dengue virus as well as other viruses." (PMID 34686207, 2021). "To validate the interaction of SidM and LidA with the identified Rab GTPases during infection, we performed co-immunoprecipitations of the effectors with Rab2A, Rab5C, and Rab10." (PMID 26755725, 2016). "On the other hand, infection with MHV-S2′FCS was significantly diminished by downregulation of the early endosomal proteins RAB5B and RAB5C, but not of the late endosomal proteins RAB7A and RAB7B or the HOPS complex components VPS11 and VPS41 (blue bars)." (PMID 25375324, 2014).
cancer (8 papers, 2014 to 2025). A tumor composed of atypical neoplastic, often pleomorphic cells that invade other tissues. "Conclusively, our study revealed that aberrant miR-145 expression affects PTC progression: miR-145 inhibition causes RAB5C overexpression and cancer progression." (PMID 32788878, 2020). "Among potential GSDMB interacting cancer and autophagy proteins, some Rab GTPases were found (Rab5C, Rab7A, Rab9A and Rab15)." (PMID 36163066, 2022). "Although previous studies have confirmed that Rab5c was an oncogene that promote cancer progression or chemoresistance through various pathways, but our research first illustrate that Rab5c act as a target of Piezo1 and activate TGF-β signaling through in cancer cells." (PMID 35461277, 2022). "To confirm the impact of altered ECM1, MBL2, BTD and RAB5C expression in existing clinical patient studies, we analysed four biomarker‐altered and non‐altered groups with a survival of 1084 patients in the pan‐cancer atlas and 2509 patients in the METABRIC data." (PMID 40545963, 2025).
RAB5C also shares sentences with these, for which no sentence is quoted: ankylosing spondylitis (1 paper); glioma (1); hepatocellular carcinoma (1); leukemia (1).